CRBN (cereblon)
Diseases named in the same sentence as CRBN in open-access papers (continued):
Sharing a sentence is not in itself a finding about the gene and the disease.
CRBN also shares sentences with these, for which no sentence is quoted: multiple myeloma (56 papers); Parkinson disease (3); B cell lymphoma (2); hepatocellular carcinoma (2); influenza (2); leukodystrophy (2); lymphoma (2); non-small cell lung carcinoma (2); tauopathies (2); acute monocytic leukaemia (1); alcoholic liver diseases (1); amnesia (1); behavioral disorders (1); brain inflammation (1); breast invasive carcinoma (1); cardiovascular disease (1); clear cell renal cell carcinoma (1); epilepsy (1); gastrointestinal disorders (1); Hyperbilirubinemia (1); Hypoalbuminemia (1); insomnia (1); Insulin resistance (1); intellectual disability syndrome (1); learning disability (1); lupus erythematosus (1); lymphedema (1); mantle cell lymphoma (1); maturity-onset diabetes of the young (1); microcephaly (1).
A further 14 diseases each share a sentence with CRBN in 1 paper.